MEN1 (menin 1)
Diseases named in the same sentence as MEN1 in open-access papers (continued):
Sharing a sentence is not in itself a finding about the gene and the disease.
liver fibrosis (2 papers, 2022 to 2025). "Clinical database analysis also revealed that Men1 expression was significantly associated with liver fibrosis." (PMID 40651612, 2025). "Men1 expression was significantly decreased in mouse liver fibrosis models induced by Methionine-Choline Deficient Diet (MCD), CCL4, and Bile Duct Ligation (BDL)." (PMID 40651612, 2025). "Men1 deficiency enhanced the sensitivity of HSCs and KCs to external environmental pathogenic factors, promoted the expression of inflammatory factors and fibrosis-related collagen, and increased the risk of liver fibrosis." (PMID 40651612, 2025). "We revealed that Men1 loss promoted CCL4- or high-fat diet-induced liver fibrosis." (PMID 40651612, 2025). "We established hepatocyte-specific Men1-KO mice (albumin-cre; Men1f/f, Men1ΔH/ΔH), and a liver fibrosis model was established by treating mice with CCL4." (PMID 40651612, 2025). "According to these results, we hypothesized that myeloid Men1 depletion induces spontaneous liver fibrosis." (PMID 40651612, 2025). "Notably, some studies also reported the profibrotic role of the Men1 gene in liver fibrosis." (PMID 35628193, 2022). "JIB-04, an H3K36me3 agonist, effectively suppressed KC activation induced by Men1 or Setd2 deletion by reactivating IL-10 expression and further alleviated CCL4-induced liver fibrosis symptoms." (PMID 40651612, 2025). "However, hepatocyte-specific Men1 deficiency did not affect the risk of liver fibrosis." (PMID 40651612, 2025).
lymphoma (2 papers, 2012 to 2023). A malignant (clonal) proliferation of B- lymphocytes or T- lymphocytes which involves the lymph nodes, bone marrow and/or extranodal sites. "We reason that expression of genes bound by high levels of MEN1/MLL1 is also hypersensitive to MEN1 inhibition, which could underline the preferential toxicity of MEN1 inhibitor to EZH2 mutant lymphoma cell lines." (PMID 37460547, 2023). "In lymphoma cells with EZH2 gain-of-function mutations, the re-localization of MLL-MEN1 complex drives oncogenic gene expression and results in a hypersensitivity to pharmacologic inhibition of MEN1." (PMID 37460547, 2023). "Furthermore, we subjected a panel of lymphoma cell lines to a small-molecule inhibitor of MEN1, MI-50354, and observed that compared to EZH2 wildtype, EZH2 mutant cells were significantly more sensitive to MEN1 inhibition." (PMID 37460547, 2023). "The detrimental effect of CRISPR-Cas9-mediated knockout of MEN1 on the proliferation of EZH2 mutant lymphoma lines KARPAS422 and SuDHL4 was also evident in competitive proliferation assays, and in xenograft experiments where depletion of MEN1 decreased the incidence of tumor formation." (PMID 37460547, 2023).
metastatic cancer (2 papers, 2021 to 2022). A carcinoma which has spread from the original site of growth to another anatomic site. "Currently, no prognostic factors allow clear identification of MEN1 patients at risk of metastatic cancers, nor to tailor personalized pNET treatment." (PMID 33919851, 2021).
nesidioblastosis (2 papers, 2022 to 2023). "Only the histological examination of a larger, representative pancreatic specimen confirmed the diagnosis of insulinomatosis and distinguished it from multifocal NET with MEN1 mutations or nesidioblastosis." (PMID 35406570, 2022).
prostate (2 papers, 2010 to 2019). "To study the occurrence of prostate lesions, we followed a male mouse cohort of 47 Men1+/- mice and 23 age-matched control littermates, starting at 18 months of age, and analysed the prostate glands from the cohort." (PMID 20663219, 2010).
pulmonary fibrosis (2 papers, 2022 to 2025). Chronic progressive interstitial lung disorder characterized by the replacement of the lung tissue by connective tissue, leading to progressive dyspnea, respiratory failure, or right heart failure. "Using knockout mouse models, a reduction of MEN1 expression has been associated with the onset of pulmonary alveolar proteinosis, which, in humans, is characterized by patients experiencing dyspnea, pulmonary fibrosis, and eventual respiratory failure." (PMID 40725399, 2025). "For instance, Wei and colleagues found that Men1 played an antifibrotic role in radiation—induced pulmonary fibrosis." (PMID 35628193, 2022). "Accordingly, this study revealed that Men1 is an antifibrotic gene in BLM—induced pulmonary fibrosis." (PMID 35628193, 2022). "Although Men1 improved BLM—induced pulmonary fibrosis in mice, the pathological process closely related to macrophages, such as pyroptosis, was still promoted by Men1 expression." (PMID 35628193, 2022). "Mice were made to overexpress or had Men1 knockdown with adeno-associated virus (AAV) infection and then induced with pulmonary fibrosis." (PMID 35628193, 2022). "To better understand this contradiction, we explored ways of Men1 in macrophages to promote pulmonary fibrosis." (PMID 35628193, 2022). "Taken together, although Men1 showed antifibrotic properties in BLM—induced pulmonary fibrosis mice, conflictive roles of Men1 were displayed in fibroblasts and macrophages." (PMID 35628193, 2022). "BLM—induced pulmonary fibrosis was attenuated by Men1 overexpression and exacerbated by Men1 knockdown." (PMID 35628193, 2022). "The results showed that Men1, which encodes menin protein, was significantly downregulated in bleomycin (BLM)—induced pulmonary fibrosis." (PMID 35628193, 2022). "In all, Men1 overexpression relieved BLM—induced pulmonary fibrosis." (PMID 35628193, 2022). "Importantly, lowered Men1 expression indeed exacerbated BLM—induced pulmonary fibrosis as the scar area further expanded and collagen deposition increased in AAV-shMen1 mice compared to that in AAV-shSC mice upon BLM treatment." (PMID 35628193, 2022). "Thus, inhibiting Men1 expression worsened the BLM—induced pulmonary fibrosis." (PMID 35628193, 2022). "This study examined the close relationship between Men1 and pulmonary fibrosis and uncovered the dichotomous roles of Men1 during BLM—induced fibrogenesis, highlighting the novel mechanism of pulmonary fibrosis and the new function of Men1 in the lung." (PMID 35628193, 2022).
rectal NETs (2 papers, 2019 to 2021). "Therefore, PHLDA3 and MEN1 LOH were also assessed in rectal NET patients for their association with clinicopathological features." (PMID 30787304, 2019). "We report here the novel finding that LOH occurs at the PHLDA3 and MEN1 loci in 60.0% and 66.7% of rectal NETs cases, respectively." (PMID 30787304, 2019). "The strikingly high incidence of LOH at these loci indicates that PHLDA3 and MEN1 are important in tumor suppression in rectal NETs." (PMID 30787304, 2019).
secondary hyperparathyroidism (2 papers, 2024). Overproduction of parathyroid hormone in response to influence external to the parathyroid glands. "Complete nuclear Menin loss is frequent in MEN1 parathyroids, which may be of help in separation from secondary hyperparathyroidism." (PMID 38244045, 2024).
somatotrophinoma (2 papers, 2014 to 2020). "Thus, our report of a patient with PNEN and somatotrophinoma who had a CDC73 variant, provides further evidence that CDC73 variants may result in a MEN1 phenocopy." (PMID 33150274, 2020). "Furthermore, a splice mutation (c.446-3c → g) has been detected in an MEN1 kindred from Tasmania, in whom there was an absence of somatotrophinomas." (PMID 23933118, 2014).
teratoma (2 papers, 2019 to 2026). A non-seminomatous germ cell tumor characterized by the presence of various tissues which correspond to the different germinal layers (endoderm, mesoderm, and ectoderm). "However, the concurrent occurrence of MEN1 and teratoma is extremely rare in reported cases to date." (PMID 41658518, 2026). "Herein, we report a case of a female patient with MEN1 who was diagnosed with teratoma." (PMID 41658518, 2026).
testis tumor (2 papers, 2019 to 2020). "Therefore, although in the absence of a direct evidence, we cannot exclude the relationship between MEN1-mutations and testis tumor development." (PMID 31249555, 2019). "The occurrence of testicular tumours was not statistically significant different between the two strains, but they were detected earlier in male 129S6/SvEv Men1+/- mice than C57BL/6 Men1+/- mice (12 vs 18 months of age (P < 0.005)." (PMID 32348957, 2020).
Uterine leiomyoma (2 papers, 2022 to 2023). The presence of a leiomyoma of the uterus. "Loss of heterozygosity at MEN1 locus was also found in esophageal and uterine leiomyomas in four of five F-MEN1 patients, whereas such loss seemed not to play a role in sporadic uterine leiomyomas." (PMID 37484956, 2023). "Sporadic MEN1 (n = 55): Uterine leiomyomas were present in nine (20%) out of 45 women." (PMID 37484956, 2023).
vitamin D deficiency (2 papers, 2021 to 2023). A nutritional condition produced by a deficiency of VITAMIN D in the diet, insufficient production of vitamin D in the skin, inadequate absorption of vitamin D from the diet, or abnormal conversion of vitamin D to its bioactive metabolites. "One study found that 21 out of 31 patients with MEN1 had 25(OH)D levels <10 ng/mL, 9 had levels between 10 and 30 ng/mL, and 1 patient had normal levels, showing the degree of vitamin D deficiency in MEN1." (PMID 38115826, 2023).
adipose tissue neoplasms (1 paper, 2022). "Prevalence of cutaneous and adipose tissue neoplasms in patients with MEN1 having a comprehensive dermatologic evaluation." (PMID 36325452, 2022).
Als (1 paper, 2025). "Menin (MEN1) is a well-recognized powerful tumor promoter in acute leukemias (ALs) with lysine methyltransferase 2A (KMT2A, previously known as MLL: mixed-lineage leukemia) rearrangements (KMT2Ar) and mutant nucleophosmin 1 (NPM1m)." (PMID 39796769, 2025). "Once MEN1 binds, KMT2A fusion proteins relocate to the nucleus, triggering the abnormal transcription of the HOXA gene and other critical genes, such as MEIS1, for the pathogenesis of KMT2Ar Als." (PMID 39796769, 2025).
amenorrhea (1 paper, 2023). The absence of menses in a woman who has achieved reproductive age. "Patients with MEN1 may have amenorrhea and reproductive disorders due to hormonal abnormalities, but, currently, there are limited studies discussing the direct impact of MEN1 mutation on fertility." (PMID 37929040, 2023).
autism (1 paper, 2024). Persistent deficits in social interaction and communication and interaction as well as a markedly restricted repertoire of activity and interest as well as repetitive patterns of behavior.
autoimmune disease (1 paper, 2021). A disorder resulting from loss of function or tissue destruction of an organ or multiple organs, arising from humoral or cellular immune responses of the individual to their own tissue constituents. "Herein, we present a case of MEN1 with multiple endocrine and autoimmune disorders." (PMID 34889280, 2021).
Autoimmunity (1 paper, 2021). The occurrence of an immune reaction against the organism's own cells or tissues. "Future cumulative clinical data may shed light on the possible role of MEN1 mutations (and type of mutations) in predisposing carriers to autoimmunity as well as for a certain phenotype, which may have implications for targeted life-long surveillance and treatment." (PMID 34889280, 2021).
benign meningioma (1 paper, 2015). A grade I, slowly growing meningioma. "Similar results were observed in an NF2-deficient benign meningioma cell line, Ben-Men1-LucB, hereafter referred to as Ben-Men, in which expression level diminished by 54% and 58% for Pak1 and Pak2, respectively." (PMID 25596744, 2015).
bowel cancer (1 paper, 2021). "While the germline alterations in certain susceptibility genes were also detected in the bowel cancer samples including FANCD2, CDH1, FLCN, MEN1, SDHB, and SLX4, which have been rarely reported in the Chinese population." (PMID 35154239, 2021).
breast NETs (1 paper, 2022). "Interestingly, in our recent study, low MEN1 protein expression was associated with poor local relapse-free survival in breast NETs." (PMID 36085291, 2022). "Furthermore, typical pathogenetic or unknown variants of PNETs and other NENs, such as ATRX, DAXX and MEN1, were very rarely detected in breast NETs." (PMID 36085291, 2022). "Thus, our breast NET material, with 6% of patients carrying MEN1 pathogenetic or unknown variants in their tumours, seems to be an intermediate form between IDCs and PNETs." (PMID 36085291, 2022). "There are, however, certain differences between breast NET and IDC mutational profiles, as exemplified by those in the MEN1 and ADCK2 genes." (PMID 36085291, 2022). "For example, MEN1 was mutated in only 6% of breast NETs and 37% in PNETs (adjusted p value 0.00050), and GATA3 pathogenetic or unknown variants were only found in 17.0% of breast NETs and 0% in PNETs (adjusted p value 0.0010)." (PMID 36085291, 2022). "Likewise, MEN1 (6%) and DAXX (2%) had rarely pathogenetic or unknown variants in breast NETs, with pathogenetic or unknown variant rates of 37% and 22% in PNETs." (PMID 36085291, 2022). "The results indicated that the MEN1 gene had the most significantly different pathogenetic or unknown variant rates in the patients of the two cohorts, being mutated in 36 out of 98 (36.7%) PNET samples in comparison to only 3 out of 53 (5.7%) breast NET samples (adjusted p value 0.00050)." (PMID 36085291, 2022). "Similarly with MEN1, these pathogenetic or unknown variants were still very rare in breast NETs: none of the samples harboured ATRX pathogenetic or unknown variants, and only one patient had a DAXX pathogenetic or unknown variants." (PMID 36085291, 2022).
chordoma (1 paper, 2023). Chordomas are rare malignant tumors arising from embryonic remnants of the notochord in axial skeleton.
cystic neoplasm (1 paper, 2025). A benign or malignant neoplasm that contains a single or multiple cystic spaces. "However, the most common molecular alterations found in ductal adenocarcinoma (KRAS), cystic neoplasms (GNAS and RNF43), and NENs (MEN1, DAXX, and ATRX) are rarely found in ACC." (PMID 41120769, 2025).
esophageal adenocarcinoma (1 paper, 2019). A malignant tumor with glandular differentiation arising predominantly from Barrett mucosa in the lower third of the esophagus. "In a review of the prognosis and survival in 1716 patients with ZES/MEN1 in the literature, no patients were reported to have an esophageal adenocarcinoma." (PMID 31623145, 2019). "In another review of 758 MEN1 patients of which 23% had ZES, no patient died from an esophageal adenocarcinoma." (PMID 31623145, 2019).
familial medullary thyroid carcinoma (1 paper, 2020). An instance of thyroid medullary carcinoma that is caused by an inherited modification of the individual's genome. "According to its clinical manifestations and types of mutation, this condition can be divided into MEN1 (Online Mendelian Inheritance in Man (OMIM) number: 131100), MEN2 and familial medullary thyroid carcinoma (FMTC) (OMIM number: 155240)." (PMID 32600305, 2020).
hearing loss (1 paper, 2021). "Thus far, there are no published reports of MEN1 and hypoacusia; however, various syndromic diseases associated with hearing loss have been reported." (PMID 33807230, 2021).
Hypocalcemia (1 paper, 2018). An abnormally decreased calcium concentration in the blood. "Post-surgical results, in restoring normal calcemia, inducing transitory and/or permanent hypocalcemia, and rate of persistence and recurrences, were comparable with data published regarding MEN1 adult patients." (PMID 30364322, 2018).
Hypokalemia (1 paper, 2019). An abnormally decreased potassium concentration in the blood. "VIP-secreting tumors or VIPomas, are rare in MEN1 and present with watery diarrhea, hypokalemia, and achlorhydria (WDHA)." (PMID 31263451, 2019).
in situ carcinoma (1 paper, 2010). A malignant epithelial neoplasm which is confined to the epithelial layer without evidence of further tissue invasion. "The prostate lesions found in heterozygous Men1 mutant mice were characterised by a slow cancer development process, which ranged from in situ carcinoma to invasive adenocarcinoma." (PMID 20663219, 2010). "CDKN1B nuclear expression was clearly reduced in an in situ carcinoma and almost absent in an adenocarcinoma from Men1+/- mice." (PMID 20663219, 2010).
Infertility (1 paper, 2023). "Within the 511 PGT FET cycles cohort, there was a rare infertility patient case complicated by MEN1." (PMID 37929040, 2023). "Applying the new rsERT along with PGT improved ART outcomes and brought awareness of the importance of the ER examination in MEN1 infertile female patients." (PMID 37929040, 2023). "The case elucidates a new angle for developing treatment guidelines for infertile patients with MEN1 by applying an integration of multiple techniques, including rsERT, PGT-M, and MDT management." (PMID 37929040, 2023). "We validated our newly developed RNA-seq–based ER test (rsERT) in a retrospective cohort study including 511 PGT cycles and reported experience in treating an infertile female patient complicated by multiple endocrine neoplasia type 1 (MEN1)." (PMID 37929040, 2023). "Second, we applied the integrated treatment scheme to an infertile female patient complicated by MEN1 who had a failed pregnancy after PGT-M embryo transfer." (PMID 37929040, 2023). "Because it is unclear how MEN1 affects fertility, clinical guidelines for the disease, particularly therapy of patients with MEN1 with infertility, are restricted." (PMID 37929040, 2023). "There are a limited number of clinical guidelines covering the treatment and management of patients with MEN1 with infertility." (PMID 37929040, 2023). "Whereas in our case, the 25-year-old female patient received an unaffected blastocyst via PGT-M but underwent an unsuccessful embryo transfer, which brings our awareness of exploring further treatment schemes in addition to PGT-M for patients with MEN1 with infertility." (PMID 37929040, 2023). "In addition, this finding also emphasizes the importance of performing MDT management for patients with MEN1 with infertility to maintain endocrine homeostasis." (PMID 37929040, 2023). "Given the achievement of clinical pregnancy via pET, which is dependent on ER prediction and WOI identification, our finding adds to the scientific debate on whether MEN1 affects infertility by providing limited evidence that MEN1 has no direct effect on ER but is impaired ER by endocrine disorders." (PMID 37929040, 2023).
large cell neuroendocrine carcinoma (1 paper, 2025). A usually aggressive carcinoma composed of large malignant cells which display neuroendocrine characteristics.